OR52W1 (olfactory receptor family 52 subfamily W member 1)
Description:
Odorant receptor.
Synonyms: OR52W1P; OR11-71
Tractability: Antibody: UniProt places it where antibodies can reach, with medium confidence; UniProt predicts a signal peptide or a membrane-spanning region; its Gene Ontology location is reachable by antibodies, with medium confidence.
Gene: Protein-coding gene on chromosome 11 (6,199,224 to 6,200,186, forward strand). Ensembl gene ENSG00000175485.
Subcellular location: Cell membrane
Pathways (Reactome):
Sensory Perception: Expression and translocation of olfactory receptors
Gene Ontology:
Molecular function: olfactory receptor activity
Biological process: detection of chemical stimulus involved in sensory perception of smell; G protein-coupled receptor signaling pathway; nervous system process
Cellular component: plasma membrane; membrane
Genetic constraint (gnomAD): Loss-of-function variants: 5 observed, 5.59 expected, observed/expected ratio (o/e) 0.89, 90% interval 0.46 to 1.73. That is too few expected variants to judge how well the gene tolerates losing a copy. Missense variants: 418 observed, 411.72 expected, observed/expected ratio (o/e) 1.02, 90% interval 0.94 to 1.1. Synonymous variants: 158 observed, 173.83 expected, observed/expected ratio (o/e) 0.91, 90% interval 0.8 to 1.04.
Homologues: Orthologues: chimpanzee OR52W1 (98% identical), macaque OR52W1 (93% identical), dog OR52W1 (86% identical), pig OR52W1 (84% identical), mouse Or52w1 (79% identical), rat Or52w1 (78% identical), rabbit OR52W1 (62% identical). Paralogues in human: OR52L1 (49% identical), OR52R1 (46% identical), OR52D1 (46% identical), OR52K2 (44% identical), OR52K1 (43% identical), OR52M1 (43% identical), OR52E8 (43% identical), OR52E2 (43% identical), OR51L1 (42% identical), OR52A5 (42% identical), OR52N4 (42% identical), OR52A1 (41% identical), and 39 more.